TLR4 (toll like receptor 4)
Diseases named in the same sentence as TLR4 in open-access papers (continued):
Sharing a sentence is not in itself a finding about the gene and the disease.
Sepsis (continued). "TLR4 is the most studied TLR, mainly because of its involvement with sepsis and septic shock." (PMID 21765613, 2011). "Our results also indicated that tag SNPs of TLR2, TLR4, TLR9, and MyD88 did not represent major risk factors for sepsis development." (PMID 21219635, 2011). "Of further interest, both Ppargc1 genes are up-regulated in sepsis through an unknown cascade involving the TLR2 and TLR4 signaling pathways." (PMID 21966468, 2011). "We examined the expression of genes of mitochondrial biogenesis program in this sepsis model in the livers of WT, TLR2−/−, and TLR4−/− mice in order to compare the wild-type response to the effects of specific innate immune receptor deficiencies on mitochondrial biogenesis." (PMID 20657826, 2010). "Moreover, evidence in the literature on the role of mast cells in innate immunity and the results presented here regarding cross-tolerance between TLR4 and TLR2 highlight the relevance of these findings with respect to sepsis." (PMID 20707930, 2010). "Lipopolysaccharide (LPS), the Gram-negative bacterial outer membrane glycolipid, induces sepsis through its interaction with myeloid differentiation protein-2 (MD-2) and Toll-like receptor 4 (TLR4)." (PMID 19816595, 2009). "To determine the effect of B. pseudomallei sepsis on TLR protein expression at the surface of peripheral blood cells, we compared the expression of CD14, TLR1, TLR2, and TLR4 on circulating monocytes and granulocytes of patients with melioidosis and healthy controls using FACS analysis." (PMID 17676990, 2007). "When TLR-4 is overactivated in sepsis, it triggers a "cytokine storm," and simply blocking TLR-4 may not restore immune balance due to the activation of compensatory pathways." (PMID 40404908, 2025). "However, the molecular mechanisms underlying the precise regulation of TLR4-dependent induction of PDPN in macrophages and the role of the PDPNhi macrophage subpopulation in sepsis immunity have not yet been elucidated." (PMID 39903516, 2025). "Another study found that protein expression levels of TLR4 and its adaptor TIRAP (TIR domain containing adaptor protein) correlated strongly with sepsis severity, suggesting that expression assays may be more clinically relevant than genotyping alone in some contexts." (PMID 41154281, 2025). "miR-146a may regulate the TLR-4/NF-κB signaling pathway via negative feedback mechanisms, leading to the improvement of the inflammatory response and cardiac dysfunction in sepsis-induced cardiomyopathy." (PMID 40041174, 2025). "To further determine whether 6 key target genes identified in this study (AKT1, MMP9, ICAM1, TLR4, BCL2, and HIF1A) could be used as therapeutic targets for sepsis and COVID-19, we downloaded the gene expression profiles of sepsis and COVID-19 patients from the GEO database (GSE95233, GSE171110)." (PMID 41411324, 2025). "It has been found that TLR4 knockout mice are resistant to Gram-negative bacteria-induced septic shock 11, and TLR2-deficient mice have increased survival rates compared to wild-type mice in a polymicrobial sepsis model." (PMID 40963927, 2025). "Thus, we propose that TLR4 may modulate NET-mediated immune reprogramming, bridging innate and adaptive immune responses in sepsis." (PMID 38888975, 2024). "Furthermore, in patients with acute myeloid leukemia, mRNA expression of TLR2 and TLR4 was found to be considerably higher in those with sepsis than in those without symptoms of sepsis prior to induction chemotherapy." (PMID 38685971, 2024). "Attempts to antagonize TLR4 have failed to improve mortality rates, suggesting that TLR4 activation may contribute to sepsis development; however, severity may be determined by a more downstream component." (PMID 39845954, 2024).
Sepsis (continued). "Despite these limitations, our discovery of pCTS-L–neutralizing mAbs capable of disrupting its interaction with TLR4 and RAGE receptors to attenuate dysregulated inflammation has suggested an exciting possibility of developing antibody strategies to fight against lethal sepsis." (PMID 36735789, 2023). "The disruption of TLR4 alone markedly reduced the pCTS-L–induced secretion of most cytokines (e.g., IL-6 and IL-12) and chemokines (e.g., RANTES, MCP-1, MIP-1γ, and LIX) except for MIP-2/GRO-β and KC/GRO-α, two neutrophilic surrogate markers of experimental sepsis." (PMID 36735789, 2023). "Compared with wild‐type mice, the TLR4 knockout decreased mortality rates, improved cardiac dysfunction, and reduced expressions of IL‐1β, IL‐6, and TNF‐α in heart tissues and decreased neutrophil infiltration in cecum ligation and puncture (CLP)‐induced sepsis mice." (PMID 38455195, 2023). "Moreover, the TLR4 pathway plays a critical role in sepsis, especially when initiated by Gram-negative bacteria, with LPS directly activating TLR4 on various immune and nonimmune cells." (PMID 37463445, 2023). "Consequently, we have obtained a panel of mAbs (2H8A2, 20D5H6, and 26C7C9) that cross-reacted with both murine and human pCTS-L to inhibit its interaction with TLR4 and RAGE receptors, thereby rescuing mice from lethal sepsis even when the first dose was given in a delayed fashion." (PMID 36735789, 2023). "Due to the fact that TLR4 inhibitors did not achieve the expectations in clinical trials as anti-sepsis drugs, LPS-mediated pyroptosis was found to be the main driver for septic shock and underlines the pivotal role of caspase-11 or caspase-4 as an LPS receptor." (PMID 37049646, 2023). "Therefore, resisting apoptosis by inhibiting the activation of TLR4/NF-κB and JAK2/STAT3 signaling pathways may have clinical benefits for patients who suffer from sepsis induced myocardial dysfunction." (PMID 37650558, 2023). "6-Gingerol-treated mice also displayed lower mortality in polymicrobial sepsis induced by CLP by enhancing bacterial clearance in the peritoneum, blood, and organs (liver, spleen, and kidney) while also suppressing the generation of TNF-α and IL-6 in TLR2 and/or TLR4-stimulated macrophages." (PMID 36588685, 2022). "This study showed that miR-146a might inhibit the TLR4/NF-κB signaling pathway through negative feedback mechanisms, thereby reducing the complications of sepsis-induced cardiomyopathy." (PMID 39281713, 2022). "In addition, extracellular IFI35 and Nmi, as two damage-associated molecular patterns (DAMPs), activated NF-κB pathway via Toll-like receptor 4 (TLR4) from macrophages, leading to the exacerbation of inflammation-related diseases such as lupus nephritis, sepsis and multiple sclerosis." (PMID 35844580, 2022). "It is noteworthy that the activation state of the TLR4 receptor was not assessed in these clinical trials prior to the recruitment of septic patients, which is understandable as there is currently no way to measure TLR4 activation in clinical material of sepsis patients." (PMID 36230982, 2022). "Moreover, mice without functional TLR4 showed a higher mortality and impaired bacterial clearance in polymicrobial sepsis or bacteria infection." (PMID 35370674, 2022). "However, a clinical trial of inhibitors of TLR4 signaling (ACCESS study reported in 2013) reported negative results, casting a shadow on the importance of LPS-TLR4-targeted therapies in sepsis." (PMID 34445610, 2021). "In renal tubular cells, XBP-1s signaling is uniquely upregulated in lipopolysaccharide (LPS) or cecal ligation and puncture sepsis-induced AKI, which is downstream of toll-like receptor 4 activation in sepsis, but not in other models of AKI or several models of CKD." (PMID 33671535, 2021). "Moreover, miR-15a down-regulates the expression level of TLR4 and IRAK1 induced by LPS, which have been more commonly related to Gram-negative sepsis, while our sepsis was all caused by Gram-positive bacteria." (PMID 34441323, 2021).
Sepsis (continued). "From a therapeutic perspective, the cell death of CD4 lymphocytes may not be modulated by TLR4 inhibition in patients with sepsis." (PMID 34733114, 2021). "Unlike LPS derived from Gram-negative bacteria that activates TLR4-expressing cells to induce sepsis, glycolipid antigens from Gram-positive pathogens such as group B Streptococci activate NKT cells in a CD1d-dependent manner, ultimately resulting in NKT cell-induced septic shock." (PMID 33809795, 2021). "The signaling cascades of TLR4-MyD88-NF-κB/MAPK could be effected by DS, thereby significantly ameliorating LPS-challenged acute kidney injury, inhibiting dimethylbenzene-induced mouse ear edema, and rescuing LPS-induced sepsis in mice." (PMID 34938184, 2021). "Importantly, the TLR4 signaling (via its adaptor TRIF) mediates a persistent injury to HSC self-renewal and repopulating functions—raising a question regarding the long-term effects of sepsis on hematopoiesis." (PMID 34367170, 2021). "However, its protective effect on TNF-α/JNK-induced hepatocyte apoptosis and on liver injury in sepsis by inhibiting TLR4/NF-κB/JNK pathways was not fully addressed." (PMID 32457606, 2020). "Activation of TLR4 signaling cascades mediates the production of proinflammatory cytokines such as TNF-α, IL-6, and IL-12, and precursor (preform) proteins of IL-1β and IL-18 (proIL-1β and proIL-18), which are critical for tissue damage and high fever during sepsis." (PMID 33042141, 2020). "Indeed, recent studies have shown that cytosolic LPS is a major driver of sepsis development and organ dysfunction without TLR4 requirement." (PMID 32332915, 2020). "However, additional physiological functions contributed by THOP1−/− mice also included a better survival and performance behavior seven days after polymicrobial sepsis induction, with a slightly lower expression of TLR4 and TNF-α in dorsal hippocampus following the sepsis." (PMID 32847123, 2020). "Several mechanisms of the release of exosomal HMGB1 from cells have been revealed so far, such as the activation of TLR4 and caspase-11/gasdermin D (GSDMD) signaling, decreased autophagy and endoplasmic reticulum (ER) stress, all of which are important cellular mechanisms of sepsis pathophysiology." (PMID 33013905, 2020). "The binding of LPS, a common PAMP present in Gram-negative bacteria, to TLR4 is believed to be an important event involved in sepsis’ inflammatory response and thus represents an essential signaling pathway to investigate in order to potentially establish new therapeutic possibilities." (PMID 33139717, 2020). "It is worth noting that in a sepsis rat model, serum-derived HMGB1 accumulates in the renal tissue and urine and turn renal tubular epithelial cells (TECs) into inflammatory promoter mediators, which facilitate the release of pro-inflammatory cytokines through binding to TLR4." (PMID 33552058, 2020). "The discrepancy might be due to the differences in the methods used to develop the sepsis model, for the TLR4 pathway was not activated in those sepses induced by Gram-positive bacteria or polymicrobia." (PMID 30915370, 2019). "To determine whether NET-induced Mφ pyroptosis following sepsis is a specific receptor-dependent event, we isolated BMDM from WT, RAGE−/−, TLR4−/−, and TLR9−/− mice, and then treated the cells with NETs (or the medium supernatant of the unstimulated PMN as a control) for 12 h." (PMID 29789550, 2018). "Moreover, blockade of TLR2 and TLR4 signaling by antagonistic antibodies successfully decreases disease severity in sepsis models of Gram-positive and Gram-negative bacteria, respectively." (PMID 28769820, 2017). "In addition, mice with a myeloid-specific-deletion of ZNRF1 are significantly resistant to both LPS- and cecal ligation and puncture (CLP)-induced sepsis and exhibit a reduced inflammatory response, demonstrating the positive regulatory role of ZNRF1 in TLR4-driven inflammatory response." (PMID 28593998, 2017).
Sepsis (continued). "TLR4 is the mammalian receptor recognizing bacterial lipopolysaccharide (LPS), the main cell wall component of Gram-negative bacteria, and plays a critical role in sepsis and controlling bacterial infections." (PMID 28804793, 2017). "However, a recent research demonstrated that eritoran, an anti-TLR4 to terminate MD2/TLR4-mediated signaling, did not significantly improve outcome for patients with severe sepsis and septic shock." (PMID 28970829, 2017). "Therefore, suppressing abnormal immune responses through TLR4-NF-κB pathway might prevent AKI and improve the clinical outcome in sepsis." (PMID 27027358, 2016). "Not surprisingly, in our TLR4+896A/G and CD14-159C/T variant alleles carriers with severe sepsis, increased TLR4 expression was accompanied by the up-regulation of in vitro LPS-stimulated NFκB, TNF-α, and iNOS signals on their cultured non-classical (CD16+, inflammatory) monocytes." (PMID 27861595, 2016). "TLR4 were mainly responded to PAMPs (such as LPS) and DAMPs (such as HMGB1), whose excessive activation could stimulate macrophages, DCs, and neutrophils which play a vital role in adaptive immunity by contributing to sepsis." (PMID 28082984, 2016). "In vivo cobalt alone independent of TLR4 induce extreme inflammatory bone loss and the addition of LPS did not significantly contribute to this response, despite the use of TLR agonists (LPS) at levels higher than those found systemically in fatal sepsis." (PMID 27467577, 2016). "Furthermore, mammalian toll-like receptors (TLR)-dependent pathway is also found to involve in the process of sepsis-induced apoptosis, which was confirmed by several studies: (i) apoptosis of spleen DCs from CLP performed on TLR4−/−, TLR2−/−, and TLR2−/− TLR4−/− was inhibited." (PMID 25821827, 2015). "Despite the critical importance of TLR signaling pathways in the pathogenesis of sepsis, recent clinical trials with eritoran (a synthetic inhibitor of MD2-TLR4) and TAK-242 (a small molecule inhibitor of TLR4 signaling) failed to improve the survival of patients with severe sepsis." (PMID 25766838, 2015). "However, this is the first study to compare the effects of single or combined administration of mAbs that block TLR2 or TLR4 with or without antibiotics in polymicrobial sepsis." (PMID 26147469, 2015). "Failure in the recent clinical trial of TAK-242, a small molecule inhibitor of TLR4, and that of eritoran, a specific antagonist of MD2-TLR4, for patients with severe sepsis have cast a shadow on the idea to target TLR4 to develop novel therapeutic interventions for sepsis." (PMID 25766838, 2015). "However, due to the complexity of sepsis pathogenesis, it is yet early to rule out targeting specific component(s) of the TLR4 signaling pathway for sepsis treatment." (PMID 25766838, 2015). "While TsES did not affect expression of TLR2 and TLR4 during sepsis, it might still regulate other TLR expressions and should be further investigated." (PMID 25054155, 2014). "Furthermore, there were no SOFA and APACHE II score differences regarding the TLR4 rs11536889 genotypes at sepsis onset, and there were no significant preexisting conditions differences between the TLR4 rs11536889 genotypes." (PMID 24950711, 2014). "However no rheological effects of sepsis or TLR4 inhibition were noted in the current study, and light microscopy revealed no convincing evidence of general or widely spread structural damage to the tubules." (PMID 25182709, 2014). "Finally, the rat monoclonal antibody 1A6, that recognizes both mouse and human TLR4-MD-2 complexes, conferred protection in a model of E. coli sepsis, but not Salmonella enterica, sepsis." (PMID 24302927, 2013). "This may have contributed to the disappointing results of the application of Eritoran (E5564), a TLR4 antagonist, evaluated in the ACCESS (A Controlled Comparison of Eritoran and Placebo in Patients with Severe Sepsis) trial, a global, randomized, double-blind, placebo-controlled Phase III study." (PMID 23690658, 2013).
Sepsis (continued). "Finally, we determined that expression of TLR2 and TLR4 is mostly intracellular in circulating human NK cells and that these receptors are upregulated differentially in and on NK cells of SIRS and sepsis patients, allowing discrimination of these two groups of patients." (PMID 23098236, 2012). "In this regard, blocking TLR4 signaling activation using a decoy receptor could be an effective way to prevent LPS- or Gram-negative bacteria-induced sepsis if applied prior to or after challenge." (PMID 19816595, 2009). "Therefore, the trial of blocking TLR4 using a decoy receptor in preventing sepsis under in vivo conditions has not been achieved until now." (PMID 19816595, 2009). "Our negative findings may be due to the fact that our population differs from the previous reported studies showing a positive correlation, e.g. studies of meningococcal disease alone (PAI-1, TLR4 and TNF-α) and of patients with severe sepsis in intensive care settings (TNF-α and TLR4)." (PMID 17877801, 2007). "Herein, activation of the TLR4/NF-κB axis in LPS-stimulated RAW 264.7 macrophages was sharply repressed by Rosuvastatin, implying that the suppressed NF-κB signaling might be responsible for the inhibition by Rosuvastatin on the activity of macrophages during sepsis." (PMID 38885061, 2024). "Additionally, the present study was only performed to preliminarily examine the roles of TLR4 in Paneth cells in sepsis, but which might not be direct, and perhaps TLR4 mediated an interesting link between Paneth cells and intestinal stem cells." (PMID 36088483, 2022). "More importantly, in this study we discovered TLR4 inhibitors(TAK-242) could improve various indicators of excessive ER stress, inculding downregulating the level of ATF6 mRNA, reducing the cleavage of ATF6 and in turn reducing the expression of CHOP compared with the sepsis group." (PMID 36088483, 2022). "Hence, the combination of TLR4 and CD40L could predict the early diagnosis and severity of sepsis." (PMID 35464001, 2022). "Notably, LPS could react with toll like receptor 4 (TLR4), inducing phagocytic cells to generate a variety of proinflammatory cytokines, such as IL-1β, tumor necrosis factor α (TNF-α), and IL-6, which is suggested to be a key pathway in sepsis pathophysiology." (PMID 34055659, 2021). "However, LPS is a classical TLR-4 agonist and induces a rapid and transient immune response, which neither reflects the much milder and protracted elevation of circulating cytokines nor the hemodynamic changes occurring in human sepsis." (PMID 33989306, 2021). "In addition to LPS administration, cell-surface proteins from gram-positive bacteria such as the M1 protein of Streptococcus pyogenes can be used to mimic sepsis that does not engage TLR4, but rather stimulates the immune system via super-antigens or peptidoglycans." (PMID 31379873, 2019). "Indeed, sepsis therapies completely blocking TLR4 have not been clinically successful." (PMID 29434211, 2018). "In addition, TLR4 knockout mice are resistant to Gram-negative bacteria-induced septic shock, and TLR2-deficient mice have increased survival rates compared to wild type mice in a polymicrobial sepsis model." (PMID 28769820, 2017). "Finally, the inflammatory responses of the septic patients could be triggered by multiple TLR pathways, and blocking one of them (even though TLR4 has been considered the major one) may not be enough to stop the overwhelming inflammation in severe sepsis." (PMID 28769820, 2017). "However, it is unknown if TLR4 mediates IFNα/β production by systemic cells, and ISG expression is equally elevated in some healthy subjects, suggesting that sepsis is not the major cause of ISG expression." (PMID 27606687, 2016).